CD4 (CD4 molecule)
Diseases named in the same sentence as CD4 in open-access papers (continued):
Sharing a sentence is not in itself a finding about the gene and the disease.
tumor (continued). "In this respect, tumor-resident CD4 TRM might reveal useful to provide local help to CD8 ACT products, and by that their function and survival." (PMID 32973794, 2020). "However, CD4+T cells can play a direct role in killing tumor cells via secretion of cytokines in addition to its traditional helper role." (PMID 32148558, 2020). "In addition, expression of IFNγ was also measured in CD4+ T cells and in NK cells in the spleen and tumor." (PMID 33584714, 2020). "Additionally, tumor growth increases the recruitment of CD4+ regulatory T cells that secrete IL-10 and TGF-β and suppress effector CD8+ T cell responses." (PMID 31938023, 2020). "Thus, we sought to circumvent restrictions of absent HLA class II expression on tumors and the limited capacity of antigen cross-presentation of APC, by enabling CD4+ T cell to directly interact with tumor cells by introducing an MHC class I-restricted TCR." (PMID 32610710, 2020). "Indeed, we found an increased frequency of IL-17A and IL-22 producing CD4+ T cells in the tumor compared with adjacent normal tissue in patients with CRC." (PMID 32451418, 2020). "Recently, Ding and co-authors showed that co-administration of IL-7 with tumour-reactive CD4+ Th cells promoted their expansion, persistence and anti-tumour activity in a mouse model, thus providing a rationale for using IL-7 as an adjuvant for CD4+ Th cell-based adoptive immunotherapy." (PMID 32183246, 2020). "Furthermore, PD-1 expression decreased and CD25 expression increased on CD4+ T cells post-tumor resection." (PMID 33374542, 2020). "The CD4+ T-cells or helper T cells play a key role in antigen-specific anti-tumor responses." (PMID 32636725, 2020). "The most striking difference observed was a strong increase in the infiltration of CD4 T cells into the tumor microenvironment of preimmunized mice (Fig EV5B) that was observed in the treated tumors but not as clearly in the contralateral ones in which only a tendency was observed." (PMID 31746149, 2020). "Notably, evaluation of neoplastic cells at T60 revealed a still low tumor burden with 0.7 × 103/ml SS cells representing 39% of CD4+ T cells (2 × 103/ml) and 16% of CD45+ leukocytes (4.4 × 103, data not shown)." (PMID 33072126, 2020). "Moreover, the numbers of CD8+, CD4+, and FoxP3+ cells infiltrating the tumours around the cryotherapeutic zones were decreased after cryoablation." (PMID 32575734, 2020). "One of the major effects of this upregulation is the inhibition of T cell activity (CD8+ effectors and CD4+ helpers which integrate adaptive and innate effector mechanisms) and the ensuing suppression of tumor immunity as a major mechanism of immune resistance." (PMID 32164265, 2020). "Remarkably, we found the inhibition of RAS markedly attenuated tumor-infiltrating CD4+ T cells." (PMID 32448803, 2020). "Interestingly, we also found that transplant tumor cure by anti-PD-1 and RT was dependent on CD4+ T cells." (PMID 33335088, 2020). "In pre-clinical cancer models, Lag-3 expression has been found to be co-expressed with PD-1 on tumor-infiltrating CD4+ and CD8+ T cells and co-blockade of Lag-3 and PD-1 can improve the proliferation and cytokine production of tumor-antigen specific CD8+ T cells." (PMID 33101304, 2020). "The correlation between LGALS3 expression and the infiltration of multiple intra-tumoral immune cell types, including B cells (CD20), T cells (CD4 and CD8), macrophages (CD68), and M2 tumor-associated macrophages (CD163), was evaluated by Spearman correlation analysis." (PMID 32528967, 2020). "Furthermore, the CD4+ and CD8+ cell population and tumor‐associated macrophages (F4/80+) in tumor tissues were decreased after treatment of ZrC@prodrug, implying that the intratumor immune response was also altered in TME." (PMID 33344115, 2020). "Importantly, TLR8 signaling reverses the suppressive functions of human tumor-derived CD4+ T cells, CD8+ T cells, and γδ T cells." (PMID 33102225, 2020).
tumor (continued). "Combinatorial therapy could enhance the infiltration of CD8+ CTLs, CD4+ T cells, Th1, Th9 cells, and M1 macrophages in the tumor, as well as anti-tumor cytokine IFN-γ." (PMID 33456484, 2020). "Animal studies on inoculated tumors, such as bladder cancer and renal cell carcinoma, showed the anti-tumor effects of mogamulizumab or Affi-5 (monoclonal antibodies targeting CCR4) which reduced the number of Treg and increased the number of NK cells and CD4+ T cells in the tumor." (PMID 33182504, 2020). "Thus, the CCL3/CCL5–CCR5 and CCL5–CCR3 axes appear to play a role in CD4+ T cell infiltration in the tumour." (PMID 32439888, 2020). "To assess if SCARF1 could functionally contribute to the balance of immune effector vs. immunosuppressive subsets within the tumor microenvironment, we studied its role in CD4+ T cell subset recruitment." (PMID 34354939, 2020). "To confirm that the CD4 THD burst was associated with a greater increase in tumor burden, we compared the TGRs in non-responder patients with and without CD4 THD burst." (PMID 32033028, 2020). "Moreover, treatment significantly increased T lymphocyte tumor infiltration, both CD4 and CD8 T cells." (PMID 33330068, 2020). "Given the importance of CD4 help function in anti-tumor CD8 responses, it is likely that CD4 responses might be required systemically to achieve efficacious CD8 responses under PD-L1/PD-1 blockade therapy." (PMID 33329566, 2020). "In another study, it was demonstrated that most of the intra-tumor CD4+Foxp3+ Treg cells have a Helios+, CTLA-4+, and CD39+ phenotype, but 30% of CD4+Foxp3− cells also expressed markers associated with regulatory functions, including CD25, LAG-3, and latency-associated peptide (LAP)." (PMID 32674255, 2020). "In such metabolic scenario, CD8+ tumor-infiltrating cells have been characterized to be unable to efficiently uptake glucose and to have hyperpolarized, fragmented mitochondria generating large amounts of mROS, otherwise required for CD4+ T cell activation." (PMID 32185131, 2020). "Changes in tumor-associated lymphocytes (e.g., CD3+, CD4+, and CD8+), upregulation of INF-gamma stimulated genes in tumor transcripts, and increase in chemokines (e.g., CXCL9 and CXCL10) were observed, while no significant change in PD-L1 expression under nivolumab treatment was reported." (PMID 32630154, 2020). "In addition, DC pulsed with TDE are more effective in stimulating CD4 + T cell proliferation in vitro, Th1 cytokine secretion and tumour-specific CTL responses." (PMID 32942702, 2020). "These CD4 effector T cells elicited by anti-CTLA-4 mAb improved anti-tumor responses by enhancing CD8 T cell infiltration, and cytolytic CD8 activity, demonstrating that PD-1 and CTLA-4 attenuate T cell activation though distinct molecular and cellular mechanisms." (PMID 32655545, 2020). "This suggests accumulation of CD4 T cells, particularly regulatory T cells, in the tumor center could impair the ability of CD8 T cells to expand in response to antigens (i.e., drive up clonality)." (PMID 32001676, 2020). "The analysis of fresh CRC specimens indicated an increased infiltration of CD4+ T cells producing IL-22 by trend compared with adjacent normal colon tissue (frequency of IL-22-producing cells within CD4+ T cells: control: 5.09±5.5 vs tumor: 7.68±6.21, p = 0.0879)." (PMID 32451418, 2020). "Results can be further investigated by in vitro MoDCs-T cells co-culture experiments to verify the outcome of the DC-T cell interaction, generating subsets of CD4+ T cells such as T helper 1 (Th1) cells, Th2 cells, regulatory T cells, or tumor-reactive CD8+ cytotoxic T cells." (PMID 33260400, 2020). "Increasing the dose to 20 Gy doubled the proportion of tumor‐infiltrating CD4+ Tregs, suggesting Tregs were more radioresistant than other cells, and may mediate immune evasion during treatment." (PMID 32994997, 2020). "Tumor-infiltrated lymphocytes (TILs) were found to be positive for CD4, CD8, and PD-1." (PMID 32751195, 2020).
tumor (continued). "B-cells can also present tumor antigens to naïve CD4+ T-cells." (PMID 33348704, 2020). "Second, C2 expression is found to be associated with tumor-infiltrating cells, such as CD4 T cells and macrophage M0 cells, but we do not explore how C2 regulate these immune cells to influence the prognosis of HCC patients." (PMID 32626741, 2020). "A clear upregulation of both PD-1 (on CD4 and CD8 T-cells) as well as PD-L1 (on tumor cells and CD4 and CD8 T-cells) was detected in response to CEA-TCB treatment, indicative of the PD-1/PD-L1 axis being one of the adaptive resistance mechanisms related to TCB activity." (PMID 33330050, 2020). "Indeed, the density of CD146 expressed on tumor-infiltrating CD4+ T cells is higher than that on peripheral T cells." (PMID 33352759, 2020). "The proportion of CD4+ T-cells expressing PD-1 was generally lower compared to CD8+ T-cells but still significantly elevated in the tumor and ascites (40.6% of tumor-derived and 19.3% of ascites-derived CD4+ T-cells) compared to healthy individuals and patient blood (0.7% and 4.6%, respectively)." (PMID 32832572, 2020). "Its inhibition downregulates MHC class II expression on TAM and DC, and repolarizes TAM, DC, and MDSC toward the M1 phenotype that promotes the proliferation and activity of CD8+ tumor-destroying cytotoxic T cells, and that abrogates CD4+ immune-suppressive regulatory T cells." (PMID 32887380, 2020). "Treatment of mice with established B16-OVA tumors or EL4-OVA tumors with IWP-L6 or C59 delayed tumor growth, and this was due to marked increase in tumor-antigen-specific CD4+ and CD8+ effector T cells with reduced number of Tregs, IL-10+ Tr1, and IL-10+ CD8 T cells within the tumors." (PMID 32132993, 2020). "Interestingly, the CD4+ cell proportion and CD4+/CD8+ cell ratio in tumor tissue were significantly decreased in the recurrent patients compared with the disease-free patients, while the CD8+ cell proportion was significantly increased." (PMID 32131750, 2020). "Thus IL-2 is critical for GzmB expression by endogenous tumor-infiltrating CD4+ T cells with little impact on other features of CD4+ T cell activation and differentiation in response to αCTLA-4." (PMID 31924474, 2020). "In vitro cocultured human CD4+ T cells were utilized in this study, which may have metabolic differences compared with primary CD4+ T cells in the tumor microenvironment of fresh human OC tissue samples." (PMID 33102225, 2020). "Moreover, the number of Ki-67-positive tumour cells and that of tumour-infiltrating not only CD11c+ and OX-62+ cells but also CD4+ and CD8+ cells were compared among the four groups via one-way ANOVA using Tukey’s multiple-comparison test." (PMID 32541941, 2020). "We also found high counts of CD4+ cells at the IM which were associated with significantly smaller tumor size (T1-T2 stage) and lymph node-negative disease at diagnosis." (PMID 33211709, 2020). "Additionally, a recent study by the group of Krummel identified cDC2s in mice and men trafficking from tumors to draining lymph nodes presenting tumor antigens to conventional CD4+ T cells." (PMID 32674488, 2020). "However, another study shows that trichostatin A can inhibit apoptosis of tumor infiltrating CD4 T cells by suppressing NFAT1-regulated Fas ligand expression on activated CD4 T cells and thereby enhance anti-tumor immune responses." (PMID 32162275, 2020). "In the tumor, MDSCs contribute to suppressing CD4+ and CD8+ T cell function." (PMID 33022971, 2020). "Flow cytometry used to analyze immune cell populations in the tumor mass indicated that the triple immune therapy was capable of significantly enhancing the natural killer cell counts as well as the CD3+CD4+/Treg and CD3+CD8+/Treg ratios possibly enhancing the anti-tumorigenic environment." (PMID 32596146, 2020). "Moreover, TGF-β-secreting cells such as TAMs and tumor cells suppress T cells, NK cells, decline DC migration, and promote CD4+ T cell differentiation into Th2 and Tregs." (PMID 32499786, 2020).
tumor (continued). "CC could target regulatory T-cells and convert them into CD4+ Th1 cells to process anti-tumor effects, and improve the imbalance of Th1/Th2 subsets to process anti-inflammatory and anti-autoimmune effects." (PMID 32344708, 2020). "We hypothesized that enhanced delivery of peptide antigens to, and uptake in, secondary lymphoid tissues should elicit more robust CD8+ and CD4+ T cell responses and improved anti-tumor responses." (PMID 33298945, 2020). "Moreover, type I IFNs make dendritic cells (DCs) mature and present-tumor specific antigens to CD4+ and protective CD8+ T cells." (PMID 32887628, 2020). "MDSCs also exert immunosuppressive features by skewing anti-tumor immune cells subsets toward immune suppressive counterparts, for example, through the conversion of naïve CD4+ T cells into Tregs and polarization of macrophages toward an alternatively activated macrophages (M2) phenotype." (PMID 33133086, 2020). "In a preventive vaccination setting, injection of irradiated autologous iPSCs plus CpG resulted in the production of tumor-reactive antibodies, expansion of effector/memory helper T cells and mature DCs as well as in a significant decrease in CD4+CD25+FoxP3+ regulatory T cells (T-regs)." (PMID 33266109, 2020). "In addition to indirect effects, such as CD8+ T cell priming and the induction of cytokine production, CD4+ T cells can also directly eliminate tumor cells by cytolytic mechanisms via their cytotoxic potential." (PMID 32802733, 2020). "In addition to CD8+ T cells, IFNγ-expressing CD4+ T cells, and NK cells have potent anti-tumor effects in the immune microenvironment." (PMID 32457755, 2020). "Moreover, senescence-related immune surveillance plays an important role through SASP factors and infiltrating immunocytes such as CD4+ Th1 cells and M1 macrophages, which can promote the clearance of senescent precancerous cells and restrict tumor formation." (PMID 33330071, 2020). "TCR‐based trajectory analysis reveals that tumor‐associated DPT clusters share separated ancestries with local CD4+ or CD8+SPT cells rather than CD3+PBMC cells." (PMID 32670760, 2020). "There are few previous studies that investigated tumor-infiltrating CD4+ T cells." (PMID 33379384, 2020). "It is widely known that CD8+ and CD4+ T cells participate in an anti-tumor immune response that could be capable of eliminating tumors even those at advanced stages." (PMID 32244885, 2020). "CHST4 may also recruit CD4+ T cells, macrophages, dendritic cells, and neutrophils into the tumor microenvironment to inhibit the progression of HBV-HCC." (PMID 33178582, 2020). "Flow cytometry analysis of co-cultured cells upon treatment revealed dose-dependent upregulation of PD-L1 on tumor cells and dose-dependent upregulation of PD-1 and PD-L1 on CD4+ and CD8+ T-cells compared with cells incubated with untargeted TCB control." (PMID 33330050, 2020). "Similarly, the expression of BTN3A1, CSF2RB, GIMAP7, GZMB, HCLS1, LCP2, and SELL was positively correlated with the infiltration of B cells, CD8+ T cells, CD4+ T cells, neutrophil, and DCs, but was negatively correlated with the tumor purity." (PMID 33042828, 2020). "Similarly, there was a reduction in the frequency of both CD8+ and CD4+ T cells in tumor-infiltrating lymphocytes (TILs) in the (OT-II-Th9 + LB-100) group as compared to Th9 group." (PMID 32620893, 2020). "Altogether, our data suggest that TIM-3 expression on CD4+ TILs could trigger pathways involved in tumor metastasis." (PMID 32041340, 2020). "Notably, CD4+ T cells are known to support survival and memory formation of tumor-specific multifunctional CD8+ T cells." (PMID 33105813, 2020).
tumor (continued). "MSC2-mediated alleviation of antigen-presenting capacity of tumor-infiltrating DCs resulted in unoptimal activation of naïve CD4+ and CD8+T lymphocytes which led to the reduced presence of effector CD4+Th1 and Th17 cells and CD8+CTLs in the tumors of B16F10+MSC14d-treated mice." (PMID 32695181, 2020). "In addition, it is also expressed on the cell membrane of tumor-infiltrating lymphocytes, activated CD4 + and CD8 + T cells, and regulatory T cells." (PMID 33196683, 2020). "Furthermore, CD4+ tumor-infiltrating T helper cells from FL patients showed a skewing towards an effector memory phenotype, while naive and central memory cells were decreased." (PMID 33353234, 2020). "Tumor-dominating CD4+ T cells play a major role in the pathophysiology of tumor." (PMID 32513132, 2020). "As expected, the frequency of TERT Th1 responders against the UCP peptide pool was greater in localized vs metastatic NSCLC (45% vs. 24%, respectively), pointing to a link between functional anti-TERT CD4 T cell immunity in peripheral blood and tumor progression." (PMID 32630460, 2020). "This fact raises the question of whether the invasion of TDLNs during tumor spreading produces an accumulation of immunosuppressive cells—like FOXP3+ CD4+ regulatory T cells (Tregs)—and imparts a tolerogenic microenvironment." (PMID 32601304, 2020). "The authors speculated that other irrelevant antigens may be used similarly, and had previously shown that injecting the pan MHC class II-binding peptide (pan HLA-DR reactive epitope; PADRE) helped control tumours through the generation of CD4+ T helper cells." (PMID 33352882, 2020). "Notably, the orchestration of naïve CD4+ T cells’ differentiation into Th1, Th2, Th17, Th9, Th22, and Tregs is crucial to remove the immunosuppressive constrains from the tumor environment and to boost effector T-cell activity." (PMID 32823814, 2020). "Overall, a complete shift of the intratumoral immune compartment towards an anti-tumor environment was established in Mye-Tet2 null mice: the levels of both CD4+ and CD8+ T-cells increased, whereas the percentage of the immunosuppressive Tregs was mildly decreased." (PMID 33212945, 2020). "In this study, we propose a mathematical model, in the form of a system of nonlinear ordinary differential equations, that predicts the interaction between tumor cells and natural killer cells, CD4+T cells, CD8+T cells, and circulating lymphocytes with or without immunotherapy and/or chemotherapy." (PMID 32148558, 2020). "Therefore, the cytotoxicity of CD4+ TH cells toward tumor cells is likely cancer type specific, presumably depends on the MHC-II expression level of different tumor cell types." (PMID 33329692, 2020). "However, the analysis of the number of CD8+ and CD4+ T cells showed the highest tumor infiltration by both types of lymphocytes in Id1 knockout mice bearing Id1-silenced tumor cells treated with anti-PD-1 therapy." (PMID 33126649, 2020). "It is further shown that the primary tumor environment promotes the differentiation of helper T cells (CD4+), and the tumor-specific Th17 cells expressing RANKL, which stimulates osteoclast activation and induces osteolytic bone lesions, ultimately promoting breast cancer colonization in the bone." (PMID 33162934, 2020). "IL-35 might limit the anti-tumour immune response by upregulating the proportions of Tregs and MDSCs and by reducing the proportions of CD4+ and CD8+ T cells." (PMID 33041668, 2020). "Moreover, a role for tumor cDC2s in inducing activation of CD4+ T cells towards IL-17-producing T lymphocytes has also been described." (PMID 32486257, 2020). "In addition, histone deacetylase inhibitors also regulate the anti-tumor immune response of tumor-infiltrating CD4 + T cells." (PMID 31838573, 2020). "Further, the Kaplan-Meier analysis demonstrated that low CD8+ T cell and CD4+ T cell infiltration in TCGA BRCA tumor samples could predict a poor prognosis (P<0.05)." (PMID 33344235, 2020).